IL6 (interleukin 6)
Diseases named in the same sentence as IL6 in open-access papers (continued):
Sharing a sentence is not in itself a finding about the gene and the disease.
acute respiratory distress syndrome (continued). "Since a decrease in theSpO2/FiO2 ratio was due to an acute respiratory distress syndrome (ARDS) manifestation, the correlation betweenSpO2/FiO2 ratio with ferritin and fibrinogen was investigated to determine whether the epithelial damage affected IL-6 and other inflammatory variables." (PMID 37841828, 2022). "Levels of inflammatory cytokines and chemokines (IL-1, IL-6 and TNF-α) increase to a delayed peak at this stage while lymphocyte levels are low and inflammatory dysregulation develops into acute respiratory distress syndrome (ARDS)." (PMID 34858409, 2021). "The ·OH radical is known to have a role in inducing IL-6 cytokine, which is a proinflammation agent that appears as a cytokine storm syndrome (CSS) marker, as found in patients with acute respiratory distress syndrome (ARDS)." (PMID 34367545, 2021). "In this study we showed for the first time that epithelial production and secretion of IL-6 and MCP-1, two important cytokines in the development of Acute Lung Injury (ALI) and Acute Respiratory Distress Syndrome (ARDS), can occur independently of F-actin and α-tubulin cytoskeletal rearrangements." (PMID 26001192, 2015). "This exaggerated response leads to the production of a number of pro-inflammatory cytokines including IL-1β, IL-2, IL-6, IFN-γ, and TNF-α, which can lead to endothelial cell injury, acute lung injury (ALI), acute respiratory distress syndrome (ARDS), and vascular collapse (shock)." (PMID 24141285, 2013). "This recognition leads to the production of pro-inflammatory cytokines, including TNF, IL-6, IL-8, and IFN-α/β, resulting in symptoms such as fever, cough, rhinorrhea, sore throat, myalgia and, in severe cases, acute respiratory distress syndrome (ARDS) and pulmonary failure." (PMID 41012635, 2025). "Similarly, specific cytokines such as IL-6, IL-8, and IL-10 have all been found at higher levels in blood derived from SARS-CoV-2-infected patients who experienced acute respiratory distress syndrome (ARDS)." (PMID 36865568, 2022). "In fact, if elevated IL-6 levels were found in severe COVID-19 patients, their levels resulted lower than those usually observed in (non-COVID-19) acute respiratory distress syndrome (ARDS) patients." (PMID 33050220, 2020). "More particular markers, such as interleukin-6, interleukin-1, and TNF-α, play an important role in disease severity, especially in patients with acute respiratory distress syndrome (ARDS), but they are more expensive and not readily available for routine clinical use." (PMID 40428888, 2025). "Similarly, in a mouse model of acute respiratory distress syndrome (ARDS), treatment with THC led to a 100% survival rate, a reduction in the infiltration of immune cells into the lungs, and a reduction in the proinflammatory cytokines IFN-γ, IL-1β, IL-2, IL-6, and TNF-α." (PMID 38202234, 2023).
inflammatory bowel disease (390 papers, 2008 to 2026). A spectrum of small and large bowel inflammatory diseases of unknown etiology. "The clinical relevance of this mechanism is underscored by human genetic studies associating ATG16L1 polymorphisms (e.g., T300A) with exaggerated IL-1β and IL-6 production in inflammatory bowel disease." (PMID 41522448, 2025). "This is clinically relevant, as high IL-6 levels are linked to chronic inflammation, playing a role in inflammatory bowel disease and other inflammatory disorders." (PMID 38751719, 2024). "Proteobacteria is commonly used as a microbial signature of disease, mainly involving inflammatory bowel disease and metabolic disorders, which is a positive association with IL-6 and IFN-γ." (PMID 39765473, 2024). "This includes increased urinary adiponectin, lipocalin-2, leptin and interleukin-6 (IL-6) levels in renal diseases and an association of elevated urinary chemerin as well as urinary and fecal lipocalin-2 levels with active inflammatory bowel diseases." (PMID 37189804, 2023). "Given the fact that IL-6 is clearly implicated in inflammatory bowel disease and other chronic diseases and cancer, its serum levels are considered markers of inflammatory diseases and anti-IL-6 treatments are under investigation." (PMID 36142723, 2022). "Dysregulated production of interleukin (IL)-6 is implicated in the pathology of inflammatory bowel disease (IBD)." (PMID 35842694, 2022). "The expression of IL-34 increases with inflammation in patients with inflammatory bowel disease and experimental colitis and is associated with an elevated TNFα and IL-6 expression." (PMID 29472590, 2018). "The use of these molecules in several mouse models has given valuable insight into IL-6 biology, e.g., antigen-induced arthritis, inflammatory bowel disease, colitis associated cancer, pancreatitis induced acute lung injury, and hepatocellular carcinoma model." (PMID 28642760, 2017). "Increased IL-6 production by macrophages, T lymphocytes, and intestinal epithelial cells is a hallmark for the pathogenesis of inflammatory bowel disease." (PMID 27064787, 2016). "Several studies have implicated the role of TNF-α, IL-1β, IL-6 in the pathogenesis of a number of inflammatory diseases, such as inflammatory bowel disease (IBD), rheumatoid arthritis, sepsis and mucositis." (PMID 26618095, 2015). "TNFα and IL-6 in particular have been implicated in the association between chronic inflammatory conditions and growth, including environmental enteric dysfunction, inflammatory bowel disease, and juvenile arthritis." (PMID 36123771, 2022). "Furthermore, TNF-α treatment increased the expression of genes encoding various proinflammatory cytokines such as IL-6, IL-8, IL-1β, and IL-17C, involved in the progression of inflammatory bowel disease." (PMID 34208517, 2021). "Some studies have shown that inflammatory bowel disease patients have a genetic predisposition to osteoporosis, such as variations in the IL-6 and IL-1 genes, which may explain the unknown bias in the detection of BMD in ulcerative colitis patients." (PMID 32072320, 2020). "Notably, HS coexists with other inflammatory diseases where IL-6 also contributes to the development, including pyoderma gangrenosum and inflammatory bowel diseases, suggesting that they share similar immune–pathogenic pathways." (PMID 33182701, 2020). "This may be the case for interleukin-6 (IL-6), which is systemically elevated in patients with emphysema and is implicated in the pathogenesis of inflammatory bowel disease." (PMID 29178961, 2017). "Inflammatory bowel disease is associated with elevated salivary IL-6 and CRP." (PMID 24915044, 2014). "Previous studies have directly implicated the presence of TNF, IL-6, and IL-1β proinflammatory cytokines in the pathogenesis of a number of inflammatory diseases, such as inflammatory bowel disease (IBD), rheumatoid arthritis, sepsis, and most importantly, in mucositis." (PMID 22973511, 2012).
inflammatory bowel disease (continued). "This, in turn, is known to cause additional cytokine release, particularly of IL-6, a fact that may lead to exacerbation of the inflammatory bowel disease." (PMID 18371229, 2008). "Besides CRP, IL-6 was closely monitored due to the association with inflammatory bowel disease." (PMID 32188047, 2020). "Patients suffering from inflammatory bowel disease (IBD) – who have an increased risk for developing CAC – show elevated levels of IL-6 in the serum and lamina propria." (PMID 27148488, 2016). "The potential risk of bowel perforation is additionally relevant as IL-6 has also been proposed as a therapeutic target for inflammatory bowel disease (IBD)." (PMID 25478789, 2014). "Gut inflammation has been associated with an IL-6-mediated hepcidin increase in a mouse model for intestinal colitis, but results in humans with inflammatory bowel disease (IBD) are equivocal." (PMID 23460869, 2013). "Three complementary causal inference approaches support most sites as responding to IL-6, with SOCS3 (Suppressor of Cytokine Signalling 3) methylation statistically mediating inflammatory bowel disease risk." (PMID 41639309, 2026). "TNF-α and IL-6 demonstrate strong connections with numerous inflammatory conditions, encompassing inflammatory bowel disease (IBD), rheumatoid arthritis, multiple sclerosis and atherosclerosis (AS)." (PMID 41190345, 2025). "Studies have shown that IL-6 inhibitors can improve symptoms of other conditions affecting the gut, known as inflammatory bowel diseases." (PMID 39857830, 2025). "Mucosal and serum concentration of IL-6 are both increased with inflammatory bowel disease in humans and animal models." (PMID 41185633, 2025). "These include the use of biologics and small molecules that modulate inflammatory cytokines (e.g., TNF-α, IL-6, IL-17), many of which are already used in conditions such as inflammatory bowel disease." (PMID 41020835, 2025). "IL-6 inhibition emerged as an appealing therapeutic avenue in view of its clear association with the pathogenesis of many diseases, ranging from bacterial and viral infections to arthritis, inflammatory bowel diseases (IBD), and multiple sclerosis." (PMID 38980514, 2025). "In inflammatory bowel diseases (IBDs) and other inflammatory disorders, the level of IL-6 usually increases." (PMID 41373555, 2025). "Under the condition of inflammatory bowel disease, the expression of Igkv16-104 is related to immune regulation and it should connect with IL6 expression." (PMID 41373555, 2025). "In mice, it has been demonstrated that sCD14 presents protective effects in inflammatory bowel disease and that a rise in the LBP/sCD14 ratio in both humans and mice is linked to an increase in plasma IL-6." (PMID 38202282, 2024). "IL-2, IL-1β, IFN-γ, IL-6, TNF-α, and IL-8 is a pro-inflammatory cytokine associated with inflammatory bowel disease, and the pro-inflammatory cytokine response is a critical pathophysiological factor in the acceleration of the occurrence and development of UC." (PMID 39473926, 2024). "In inflammatory disorders, dysregulation of IL-6 signaling is at the core of conditions like rheumatoid arthritis, inflammatory bowel disease, and systemic lupus, exacerbating inflammation, that cause to tissue damage." (PMID 39015561, 2024). "The first selective inhibitor of IL-6 trans-signaling, olamkicept, has shown encouraging results in phase II clinical studies for inflammatory bowel disease." (PMID 39125976, 2024). "IL17‐producing cells are concentrated in the intestinal mucosa and submucosa of patients with inflammatory bowel disease, and they are functionally linked with a pro‐inflammatory role via the upregulation of TNFα, IL1B, IL6, IL8, and neutrophil recruitment." (PMID 38992956, 2024). "FDEVs reduce pro-inflammatory cytokines (IL-1β, IL-6) and increase anti-inflammatory IL-10 levels, demonstrating efficacy in mouse models of inflammatory bowel disease." (PMID 39796048, 2024).
inflammatory bowel disease (continued). "Utilizing a proinflammatory cocktail of TNF-α, IL-6, and IL-1β to mimic the inflammatory environment of inflammatory bowel disease (IBD), we observed clear differences in the cellular responses to acute versus chronic inflammation." (PMID 39489847, 2024). "Studies have shown a direct link between the level of IL-6 in the serum and the disease severity of inflammatory bowel disease." (PMID 39195452, 2024). "There has been particular interest in the role of IL-6 and IL-8 in intestinal inflammation, with inflammatory bowel disease standing as a classical pathology in which the two cytokines play a significant role." (PMID 39062898, 2024). "The first natural and specific inhibitor of IL-6 trans-signaling, olamkicept, has shown encouraging results in phase II clinical studies for inflammatory bowel disease." (PMID 39125976, 2024). "In models of inflammatory bowel disease, the up-regulation of gp130 signalling mediated by elevated levels of tumor IL-6 and IL-11 leads to Yap1 activation as a mechanism of wound healing." (PMID 37957015, 2024). "Studies on the predictors of clinical responses to biological therapy in patients with inflammatory bowel disease have focused on serum IL-6 levels." (PMID 38592255, 2024). "A study suggested a positive link between NOS-derived NO and IL-6, IL-17A, and IL-23 plasma levels in inflammatory bowel disease patients." (PMID 36986188, 2023). "which investigated the effect of soluble antigens on laminated layer of E. granulosus in inflammatory bowel disease in vivo in mice and showed that antigen B decreased the cytokines IL‐1ß, IL‐6, and TNF‐α by affecting the NF‐κB and IRAK pathways." (PMID 36582052, 2023). "The studies of Xiao-Yu Ai confirm that apigenin effectively inhibits inflammatory bowel disease and colitis-associated cancer through decreased levels of the inflammatory cytokines TNF-α, IL-1β, IL-6, MCP-1, and CSF-1 and of COX-2 in tumors." (PMID 36836951, 2023). "Pro-inflammatory cytokines play an essential role in the regulation of intestinal immunity, and among them, IL-1β, TNF-α, and IL-6 abnormalities are considered to be important in the pathogenesis of inflammatory bowel disease." (PMID 38139262, 2023). "The core pathway related to UC was inflammatory bowel disease referring to IL6, TNF, RELA, and STAT3." (PMID 36382627, 2022). "In inflammatory bowel disease, LPS or cytokines (e.g. IL-6 and IFN-γ) can activate JAK/STAT signaling pathway to regulate the expression of pro-inflammatory mediators including Claudin-2 and iNOS." (PMID 35436978, 2022). "In this regard, it has been shown in experimental mouse models of inflammatory bowel disease that increased intestinal IL-6 tissue levels correlate with decreased mucus thickness." (PMID 35431918, 2022). "Olamkicept, a highly selective IL-6 trans-signaling blocker has shown to be efficacious and safe in clinical trials involving patients with inflammatory bowel disease, another condition for which IL-6 trans-signaling is the mediating mechanism." (PMID 36778590, 2022). "IL-6 is an important cytokine of inflammatory bowel diseases, which can activate the JAK/STAT signaling pathway and promote the release of various inflammatory factors." (PMID 35436978, 2022). "For instance, the failure of anti‐IL‐6 therapy in inflammatory bowel diseases is often cited as an example of IL‐6 functional complexity." (PMID 34618359, 2022). "IL-1β and IL-6 are part of the NF-κB pathway, they are important mediators of the inflammation at the level of the intestine and have been related to inflammatory bowel diseases." (PMID 35216089, 2022). "For instance, IL-6 is involved in ‘immune response’, ‘cellular response to lipopolysaccharide’, and ‘inflammatory bowel disease’, all of which are closely related to UC." (PMID 33409535, 2021).
inflammatory bowel disease (continued). "Another small molecule inhibitor LMT-28 (a derivative of oxazolidinone) was recently demonstrated to suppress IL-6 signaling by directly binding gp130, resulting in alleviation of inflammatory diseases such as RA and inflammatory bowel disease." (PMID 34149710, 2021). "IL-6 is produced by T cells during chronic inflammation, such as inflammatory-bowel diseases and atopic dermatitis." (PMID 33171330, 2021). "In inflammatory bowel disease, IL-6 produced by macrophages mediates apoptosis resistance and abnormal accumulation of T cells in the intestinal mucosa through its classical and trans-signals and promotes the differentiation of Th17 cells." (PMID 33553436, 2021). "In most inflammatory bowel diseases, IL-1β acts together with other proinflammatory cytokines such as IL-6 and tumor necrosis factor-α or IL-23 in the inflammatory process, and treatment alone against the proinflammatory effects of IL-1β has little effect." (PMID 33553436, 2021). "Cytokines, such as IL-6, have been shown to play a crucial role in the pathogenesis of inflammatory bowel diseases (IBDs) where they act as essential drivers of the inflammatory response." (PMID 33414459, 2021). "It has been clearly demonstrated that the aberrant production of inflammatory cytokines, such as TNF-α, IL-1β and IL-6, often observed in the gut of patients with inflammatory bowel disease (IBD), is a consequence of deregulated NF-κB signaling cascade." (PMID 33652555, 2021). "Of note, TNF-α, IL-1β, and IL-6 are produced by macrophages in different inflammatory conditions, including inflammatory bowel diseases (IBD)." (PMID 34072532, 2021). "Overexpression of pro-inflammatory IL-8, along ide IL-6 and TNF-α, has been associated with inflammatory processes in the digestive system, particularly in the intestines, inducing inflammatory bowel disease (IBD)." (PMID 34203479, 2021). "Tumor necrosis factor alpha (TNF-α) and interleukin 6 (IL-6) play essential roles in the pathophysiology of inflammatory bowel disease." (PMID 32090060, 2020). "Many cytokines such as TNF-α, IL-6, and IL-1β play a key role in the pathogenicity of inflammatory bowel disease, in regulating inflammation of the intestinal mucosa, and in the integrity of the intestinal epithelium." (PMID 33204254, 2020). "One important characteristic of IL-6 is the persistent activation in the whole process of inflammatory bowel disease and CRC, while the upregulations of other cytokines like TGF-β1, IL-10, and IL-23 only show up primarily during CRC development." (PMID 32855767, 2020). "High IL-6 expression is enriched in a stromal cell subset that is rare in healthy individuals, but dramatically expanded in patients with inflammatory bowel disease (IBD)." (PMID 31156640, 2019). "Elevated levels of IL-6 have been seen in other inflammatory conditions of the gastrointestinal tract, especially inflammatory bowel disease." (PMID 30744559, 2019). "Signaling pathways activated by IL-6 have been widely investigated in terms of CRC carcinogenesis in patients with inflammatory bowel disease." (PMID 30800188, 2019). "The down-regulated IL-6 and IL-6/IL-10 ratio confirmed the anti-inflammatory effect of salidroside for enteritis and other inflammatory bowel diseases." (PMID 30944705, 2019). "Interleukin-6 (IL-6) production and signalling are increased in the inflamed mucosa in inflammatory bowel diseases (IBD)." (PMID 29748708, 2018). "Patients with inflammatory bowel disease should receive careful attention when receiving IL-6 inhibition therapy, because IL-6 has a protective effect of the intestinal epithelium." (PMID 30423923, 2018). "IL-6 plays a vital role in the chronic inflammation and pathogenesis of autoimmune diseases, especially inflammatory bowel disease." (PMID 30200658, 2018).